FLI1 (Fli-1 proto-oncogene, ETS transcription factor)
Diseases named in the same sentence as FLI1 in open-access papers (continued):
Sharing a sentence is not in itself a finding about the gene and the disease.
tumor (continued). "After 24 h under s-μg the tumor-specific main translocation-protein EWS/FLI1 was significantly upregulated in both spheroids and adherent cells compared to the 1 g control group (18.5x, 8.2x, p < 0.05 each)." (PMID 31810195, 2019). "Sustained expression of EWS/FLI1 is necessary to maintain the phenotype of this tumor, and EWS/FLI1 inhibition has been shown to reduce oncogenic transformation." (PMID 31810195, 2019). "To further understand the biological processes and networks involved in tumor malignancy based on the proteins regulated by EWS/FLI1, we performed network analyses using the Ingenuity Pathways Analysis (IPA) system (IPA; QIAGEN, Redwood City, CA, USA)." (PMID 29581854, 2018). "In the current study, we found that the expression of ERG and FLI1 in tumor ECs is downregulated because of soluble factors enriched in the tumor microenvironment." (PMID 30500808, 2018). "Extensive DNA demethylation in the promoter correlates with the upregulation of FLI1 in FECR1-expressing tumor cells." (PMID 30537986, 2018). "Knockdown of FLI1 attenuates tumor metastasis through multiple pathways, including the Rho GTPase pathway and the epithelial-mesenchymal transition pathway." (PMID 30537986, 2018). "Taken together, these data suggest that multiple cytokine dynamics rather than a single cytokine-mediated signaling would lead to EndMT via ERG and FLI1 reduction in the tumor microenvironment." (PMID 30500808, 2018). "In brief, FLI‐1 correlated positively with the tumor‐initiating capacity by influencing the CSC‐like properties." (PMID 29869379, 2018). "Histopathological evaluation revealed conventional appearance of ES as a neoplasm made up of small round cells (hematoxylin-eosin staining) and that only ES tumor cells were positive for FLI1 staining." (PMID 30140378, 2018). "Because EndMT is known to be induced in the tumor microenvironment, we investigated the expression of ERG and FLI1 in ECs in tumor tissues by immunofluorescent staining." (PMID 30500808, 2018). "We uncovered a novel pathway by which FLI1 controls tumor metastasis in conjunction with its exonic circular RNA FECR1." (PMID 30537986, 2018). "Using the R2 platform, we analyzed the expression level of EWSR1 and FLI1 in published NB tumor and cell line gene expression datasets." (PMID 29212266, 2017). "Using two SCLC cell lines as a model, we also found that knockdown of FLI1 with siRNA or shRNA promoted apoptosis and led to inhibition of cell proliferation, tumor colony formation and in vivo tumorigenicity." (PMID 28410216, 2017). "This study uncovers FLI1 as an important driving factor that promotes tumor growth in SCLC through the miR-17-92 pathway." (PMID 28410216, 2017). "Previous studies have shown that knocking-down Fli-1 leads to marked growth inhibition and death in erythroleukemic cells, indicating a possible use of Fli-1 as a therapeutic target to induce tumor suppression." (PMID 28418872, 2017). "Clinicopathologic analysis of Fli-1 expression revealed positive correlations of high Fli-1 expression with an advanced tumor stage and positive lymph nodal involvement." (PMID 28418872, 2017). "Knockdown of FLI1 with small interfering RNA (siRNA) or short hairpin RNA (shRNA) promoted apoptosis and induced repression of cell proliferation, tumor colony formation and in vivo tumorigenicity in highly aggressive SCLC cell lines." (PMID 28410216, 2017). "Compared to the shRNA control, knockdown of FLI1 significantly inhibited tumor colony formation (p < 0.05)." (PMID 28410216, 2017). "We used the transgenic zebrafish line with green fluorescent protein (GFP)-labeled blood vessels [Tg(fli1:egfp)] to facilitate the observation of tumor–endothelial cell interactions." (PMID 28968975, 2017). "Knocking down FLI-1 expression in cancer cells leads to growth inhibition and cell death, demonstrating a possible therapeutic approach to induce tumor suppression." (PMID 27304058, 2016).
tumor (continued). "In this study, we provide important evidence in support of miR-145 functioning as a tumor suppressor by targeting the expression of FLI-1 in OS." (PMID 27304058, 2016). "Immunohistochemistry demonstrated diffuse membrane positivity of the tumor cells for vimentin, FLI1 and CD99 and negativity for CKpan, CgA, Syn, CD117, HMB45, S100, CD20 and CD3." (PMID 25780425, 2015). "There was a significantly higher FLI1 expression score in collected tumor tissues than that in their adjacent tissues (P < 0.01)." (PMID 26156017, 2015). "Clinicopathologic analysis of Fli-1 expression revealed that the high expression of Fli-1 was positively correlated with advanced tumor stage and positive lymph nodal involvement." (PMID 24923303, 2014). "Knocking-down Fli-1 expression in erythroleukemic cells leads to a marked growth inhibition and cell death, demonstrating a possible therapeutic approach to induce tumor suppression." (PMID 24923303, 2014). "Insertions in both Csf1 and Fli1 were cloned from sections of fresh frozen tumor found in this mouse." (PMID 25423036, 2014). "The EWS/FLI-1 fusion presence is achieved by molecular methodology with qPCR, by using the RNA extracted from the tumor material as a biological sample." (PMID 25870707, 2014). "Histologically, the tumor has a micropolypoid growth, and tumor cells with cytoplasmic vacuoles occasionally contain erythrocytes expressing Fli-1 and CD31, which are relatively specific endothelial markers." (PMID 24942542, 2014). "We demonstrated the presence of CTCs carrying oncogenic EWS–FLI1/ERG fusions in only 19 % (n = 3) of ES patients with confirmed EWS/FLI1 rearrangements in tumor specimen." (PMID 25008066, 2014). "Tumor cells expressing Fli-1 and CD31 have been identified as relatively specific endothelial markers." (PMID 24942542, 2014). "FLI1 immunoreactivity in the same region of non-tumor bearing mice (brown staining) primarily occurred in cells with morphologic characteristics of red blood cells." (PMID 25423036, 2014). "Co-Mo or PKD1 SB-Mo I5 were injected in the 1-cell or 2-cell stage of tg(fli1:EGFP) zebrafish embryos followed by injection of a HCT116 tumor cell-matrigel solution in the perivitelline space at 48 hpf." (PMID 23874489, 2013). "Antibody against FLI1, which is centered in the nucleus of the tumor cells, has been shown to be specific for EFT." (PMID 25206203, 2013). "A recent study using both patient-derived cell lines and tumor samples from individual EWS patients demonstrated that many EWS/FLI1 upregulated genes do have roles in cell cycle control." (PMID 23857410, 2013). "The fusion transcript EWSR1/FLI1, as well as many other chimeric proteins, interferes with several molecular pathways, influencing the development and progression of this tumor." (PMID 23329308, 2013). "A nested MLR-PCR assay was developed for detection of genomic EWS-FLI1 and FLI1-EWS fusion sites from diagnostic tumor biopsy specimens." (PMID 23441188, 2013). "EWS/FLI1 induced genes are expected to work functionally like oncogenes, while EWS/FLI1 repressed genes are expected to act functionally like tumor supressor genes." (PMID 23750284, 2013). "Immunohistochemically, expression of CD31, CD34, and FLI-1 is the most reliable feature for diagnosis of this tumor." (PMID 23133773, 2012). "Suppression of EWS/FLI-1 fusion protein and decreased tumor growth was seen in ES cells in vitro and in murine models using antisense ODNs complementary to the fusion mRNA." (PMID 22523703, 2012). "Through these interactions, EWS/FLI-1 maintains a large degree of control in tumor development and progression, cell proliferation, and escape from apoptosis." (PMID 22523703, 2012).
tumor (continued). "Not only did shRNA maintain a stable knockdown of EWS/FLI-1, but also a decrease in tumorigenicity of cells and tumor growth in mice was seen." (PMID 22523703, 2012). "Another study showed knockdown of EWS/FLI-1 and suppression of tumor growth by systemic administration of siRNA in mice." (PMID 22523703, 2012). "We have demonstrated that KRAB/FLI-1 expression reduces the ability of these cells to proliferate in low serum, form colonies in soft agar and tumours in nude mice and reduced the upregulation of c-myc." (PMID 12556973, 2003). "Clones that expressed both mutant KRAB/FLI-1 and EWS/FLI-1 displayed a similar tumour growth rate in nude mice to that of the parental EWS/FLI-1-expressing cells; however, clones that expressed KRAB/FLI-1 showed significantly reduced tumour size." (PMID 12556973, 2003). "In the last tumour, the presence of at least four additional splicing variants corresponding to fusion of EWS exon 7 to FLI-1 exons 4, 6, 8 and 9 was demonstrated." (PMID 7524604, 1994). "The IHC staining was positive for CD99 and FLI-1 (in >50% of tumor cells) and negative for AE1/AE3, INI-1 loss, WT1, desmin, myogenin, BCOR, TLE-1, CD45CLA, and synaptophysin." (PMID 41230381, 2026). "FLI1 encodes a transcription factor that contains the DNA-binding domain of the E26 transforming-specific (ETS) family involved in cellular growth and angiogenesis, which induces tumor progression and metastasis." (PMID 39816677, 2025). "Collectively, our results support a mechanistic model in which LSD1–FLI1 crosstalk is involved in immune and stromal remodeling, positioning FLI1 as both a marker of tumor aggressiveness and a potential predictor of response to epigenetic therapies in breast cancer." (PMID 41300765, 2025). "Notably, molecular analysis of the tumor identified an atypical EWSR1::FLI1 rearrangement, a finding previously unreported in this malignancy, along with several pathogenic variants associated with hematologic malignancies." (PMID 40630716, 2025). "Furthermore, the transcription factors PBX1 and FLI1 exhibited higher activity in the tumour-derived T1 cluster, suggesting their potential regulatory roles in driving these downstream changes." (PMID 40427675, 2025). "Specifically, it seeks to determine whether FLI1 expression correlates with aggressive tumor characteristics and clinical outcomes, thereby providing insights into its potential as a prognostic marker." (PMID 41300765, 2025). "EWSR1::FLI1 is essential for ES cell survival and tumor growth in mice." (PMID 39894896, 2025). "Additionally, EWS::FLI1 by itself can transform primary bone marrow derived MSCs and develop tumor with EwS features including small round cells, dependence on IGF-1, and expression of EWS::FLI1 target genes." (PMID 39091911, 2024). "Lastly, mCherry-labelled EWS cells were injected into the yolk sac of fli1:EGFP ZF embryos to verify that the inhibition of SIRT1/2 via tenovin-6 halted the invasiveness of tumor cells by tracking the distance and direction of cell clusters inside the embryo in vivo." (PMID 39200384, 2024). "Accordingly, immune function regulation by targeting immune cells infiltrating the tumor microenvironment might be a crucial link between FLI1 and BRCA." (PMID 38448802, 2024). "Moreover, IDO1 reintroduction negated the suppressive impact of FLI1 KO on tumor growth and T cell exhaustion." (PMID 38816360, 2024). "Furthermore, our data supported the concept that EWS::FLI1 regulates complex networks, including those of genes connected to the epigenetic regulation of gene expression and tumor cell proliferation." (PMID 39524141, 2024). "Although FLI1 might be downregulated in tumor mass, it is exerted as an immune regulator by targeting immune cells’ receptors or ligands expression in tumor mass, further affecting the communication of cells infiltrated in the tumor." (PMID 38448802, 2024). "We would like to clarify the detailed regulatory mechanisms of FLI1 in the tumor immune field." (PMID 38448802, 2024).
tumor (continued). "Thus, our comprehensive data illuminate that tumor-intrinsic FLI1 dampens T cell-mediated immunity by potentiating the IFN-γ-IDO1-Kyn pathway, thereby conferring a survival advantage to the tumor." (PMID 38816360, 2024). "In addition to aberrant FLI-1 expression in tumour cells, reports in the literature also indicate that FLI-1 expression is dysregulated in ECs residing in the tumour microenvironment." (PMID 39107790, 2024). "A better understanding of the role of FLI-1 in ECs may facilitate the design of more effective targeted therapies for clinical applications, particularly for tumour treatment." (PMID 39107790, 2024). "Additionally, administration of YK-4-279 mirrored the effects of FLI1 KO in TME remodeling to suppress tumor growth." (PMID 38816360, 2024). "An increasing number of studies have shown that FLI-1 not only plays an important role in the development of a variety of tumours but also influences angiogenesis, suggesting that FLI-1 may be a good therapeutic target." (PMID 39107790, 2024). "In addition, malignant tumor markers including CD99, NKX2.2, and FLI1 were all highly expressed in tumor cells." (PMID 38769118, 2024). "A variety of nanomaterials, for example, N-(2-hydroxypropyl) methacrylamide copolymers, polyglutamic acid, polyethylene glycol, and carboxymethyldextran polyalcohol polymers, can deliver camptothecin (a kind of FLI-1 inhibitors) to tumour cells to improve its anticancer activity." (PMID 39107790, 2024). "Notably, in the tumour microenvironment, the downregulation of FLI-1 expression in ECs can promote the EndMT process and facilitate tumour metastasis." (PMID 39107790, 2024). "Further analyses of cellular communication revealed that, in tumor samples, the communication between intratumor cells was different from that in normal tissues, and target genes of FLI1 showed a large intersection with ligand or receptor genes mediating cellular crosstalk." (PMID 38448802, 2024). "Conversely, FLI1 was also reported to be associated with shorter survival, and FLI1 downregulation in BRCA might promote tumor progression." (PMID 38448802, 2024). "Furthermore, EWS/Fli1 transcriptional regulation can also be regulated by cell extrinsic mechanisms such as the tumor microenvironment." (PMID 38875295, 2024). "An improved understanding of FLI-1 in ECs may help in the design of more effective targeted therapies, especially for clinical application in the treatment of tumour patients." (PMID 39107790, 2024). "FLI-1 expression tended to be heterogeneous, even within the same neoplasm." (PMID 38280044, 2024). "For instance, FLI1 in myeloid cells activated MHC-II molecules’ expression, which mainly improved the tumor antigen presentation, but in the T cells, FLI1 inhibited CD8A expressions, which might harm T cell activation." (PMID 38448802, 2024). "Importantly, in alignment with in vitro findings, FLI1 KO in tumor cells correlated with a diminished proportion of exhausted CD8+ T cells." (PMID 38816360, 2024). "On the other hands, knockdown of FLI1 markedly suppressed tumor growth after radiation." (PMID 36814284, 2023). "Future studies will also need to investigate if the expression of ETS1 and the other transcription factor genes data suggests some EWS tumor cells express at higher levels than EWS cell lines is a result of heterogenous EWSR1:FLI1/ERG expression and/or due to the transduction of external stimuli." (PMID 38187702, 2023). "Additionally, EWSR1::FLI1 recruits the BAF complex to tumor-specific enhancers to promote activation of target genes." (PMID 36672331, 2023). "The EWS tumours analysed in this study had EWS translocations with FLI1 (n = 3) and ETV1 (n = 2)." (PMID 34471258, 2022). "However, only recently has the field begun to identify specific signals in the bone that can alter EWS::FLI1 activity and tumor cell phenotypes." (PMID 36505823, 2022).
tumor (continued). "Although multiple studies reveal various signaling pathways mediated by the EWSR1/FLI1 fusion, the specific transcriptional control of tumor cell resistance to doxorubicin is unknown." (PMID 36428591, 2022). "EWS::FLI1 promotes tumorigenesis, cell proliferation, and tumor expansion." (PMID 36505823, 2022). "The first clues that levels of fusion expression might contribute to cell plasticity and tumor behavior came from early studies of EWS::FLI1 knockdown." (PMID 36505823, 2022). "(D) Immunofluorescence staining of zebrafish tumor with anti-eGFP and anti-FLI1 antibodies." (PMID 35285802, 2022). "As some cancers are driven by gene translocations (e.g., Ewing sarcoma is driven by the reciprocal translocation between EWS gene and ETS transcription factor (Fli-1)), a research group aimed to detect circulating DNA fragments carrying this translocation breakpoint to assess tumor burden." (PMID 35628154, 2022). "To test whether zebrafish tumor cells express EWSR1-FLI1 on different levels we performed immunofluorescence staining of tumor sections with anti-eGFP and anti-FLI1 antibodies." (PMID 35285802, 2022). "LIN28B enhanced tumor growth by stabilizing the mRNA of EWS/FLI1 independently of let-7." (PMID 35954475, 2022). "While complex and diverse reasons are likely to underlie this, consideration must be given to the possibility that creation of subpopulations of EWS::FLI1 “low” cells by these treatments might actually support tumor progression." (PMID 36505823, 2022). "Although most investigations in this field focus on the interaction between EWS/FLI1 and intracellular pathways, several others have explored the possibility of interfering with extracellular signaling paths that regulate EWS/FLI1, and consequently, tumor transformation." (PMID 35454895, 2022). "EWSR1::FLI1 expression can vary between cells within a tumor." (PMID 36483025, 2022). "Moreover, the expression of circ-FLI1 was downregulated in xenograft tumor tissues and allied with higher miR-197-3p and lower DKC1." (PMID 35647294, 2022). "The IHC findings disclosed that smooth muscle actin (SMA) and mouse double minute 2 (MDM2) markers were positive in the majority of the tumor cells; additionally, high-molecular-weight caldesmon (h-caldesmon) and Friend leukemia insertion-1 (Fli-1) markers were positive in some tumor cells." (PMID 34715885, 2021). "In addition, Moonlight identified FLI1 as a tumor suppressor in multiple cancer types, including lung, breast, uterine, and colon." (PMID 31900418, 2020). "Given our goal of testing the antiangiogenic and metastatic impact of bevacizumab treatment in zebrafish xenografts, we analyzed tumor-induced angiogenesis by generating xenografts in Tg(fli1:eGFP) transgenic zebrafish hosts, which have the vasculature labeled with eGFP40." (PMID 32523131, 2020). "Therefore, Fli-1 as a specific target for anti-cancer drugs can regulate the proliferation, differentiation, and apoptosis of tumor cells and block the formation of tumor blood vessels for controlling cancer cell invasion and migration." (PMID 32210104, 2020). "However, it disrupted tumor formation and vascular development in a zebrafish xenograft model and angiogenesis transgenic (Tg, fli1-eGFP) model, respectively." (PMID 31936539, 2020). "We hypothesize that differentially methylated CpG islands, or hypermethylation of the FLI1 promoter, may also lead to inactivation of FLI1’s tumor-suppressor ability." (PMID 31900418, 2020). "Intriguingly, the high FLI1-expressing poorly differentiated tumors had improved survival as compared to those with low FLI1 expression, suggesting a role for FLI1 as a differentiation-dependent tumor prognostic biomarker." (PMID 31231464, 2019). "We then analyzed how nuclear FLI1 expression correlated with tumor and clinical features." (PMID 31231464, 2019).